CCS (copper chaperone for superoxide dismutase)
Description:
Delivers copper to copper zinc superoxide dismutase (SOD1).
Tractability: Small molecule: a structure with a bound ligand is known; it has a high-quality binding pocket. PROTAC: UniProt records ubiquitination sites on it; ubiquitination databases record sites on it; its protein half-life has been measured.
Gene: Protein-coding gene on chromosome 11 (66,593,153 to 66,606,019, forward strand). Ensembl gene ENSG00000173992.
Subcellular location: Cytoplasm, cytosol
Pathways (Reactome):
Cellular responses to stimuli: Detoxification of Reactive Oxygen Species
Gene Ontology:
Molecular function: cadherin binding; copper ion binding; protein binding; protein-disulfide reductase activity; superoxide dismutase copper chaperone activity; metal ion binding
Biological process: protein import into mitochondrial intermembrane space; cellular response to oxidative stress; protein maturation; removal of superoxide radicals; superoxide metabolic process
Cellular component: cytoplasm; cytosol; mitochondrial intermembrane space; mitochondrion; nucleus; superoxide dismutase copper chaperone complex
Genetic constraint (gnomAD): Loss-of-function variants: 27 observed, 31.2 expected, observed/expected ratio (o/e) 0.87, 90% interval 0.64 to 1.19. The upper end of that interval is the gene's LOEUF score, 1.19, which puts it in group 5 of 6, group 1 being the genes least tolerant of losing a copy. Missense variants: 313 observed, 341.81 expected, observed/expected ratio (o/e) 0.92, 90% interval 0.83 to 1.01. Synonymous variants: 119 observed, 134.05 expected, observed/expected ratio (o/e) 0.89, 90% interval 0.76 to 1.03.
Gene-disease validity (ClinGen):
ClinGen rates the evidence that CCS causes each of these diseases.
disorder of copper metabolism (inheritance undetermined): No Known Disease Relationship. An inherited metabolic disease that is has its basis in the disruption of cellular copper ion homeostasis.
Homologues: Orthologues: chimpanzee CCS (99% identical), macaque CCS (96% identical), rabbit CCS (95% identical), guinea pig CCS (90% identical), dog CCS (89% identical), mouse Ccs (87% identical), pig CCS (83% identical), rat Ccs (71% identical), zebrafish ccs (66% identical), tropical clawed frog ccs (62% identical), Drosophila melanogaster Ccs (46% identical). Paralogues in human: SOD1 (27% identical), SOD3 (24% identical).
Diseases named in the same sentence as CCS in open-access papers:
CCS is named in the same sentence as 45 diseases in open-access papers, as found by Europe PMC text mining. Sharing a sentence is not in itself a finding about the gene and the disease. The quoted sentences say what the papers report.
breast cancer (7 papers, 2019 to 2025). A primary or metastatic malignant neoplasm involving the breast. "Targeting CCS may represent a promising approach for selectively causing cell proliferation and migration in breast cancer cells." (PMID 31024318, 2019). "In studies of MDA‐MB‐231 cells (TNBC) and MCF‐7 cells (ER + BC), exogenous inhibitors DC_AC50 of CCS and endogenous silencing of CCS both inhibit the growth and migration of breast cancer cells by inhibiting the ROS‐mediated MAPK/ERK pathway activity." (PMID 39676279, 2024). "CCS promotes the growth and migration of breast cancer cells by regulating ROS‐mediated ERK1/2 activity." (PMID 39676279, 2024). "High expression; In MDA‐MB‐231 and MCF‐7, CCS promotes the growth and migration of breast cancer cells via regulating the ERK1/2 activity mediated by ROS." (PMID 39676279, 2024). "The Gene Expression Database of Normal and Tumor Tissues 2 (GENT2) was examined for AKT and CCS expression in patients affected by different subtypes of breast cancer, and in relation with their overall survival (OS)." (PMID 36454513, 2023). "For example, in patients with breast cancer, the levels of CCS were increased along with the ability of CCS to promote proliferation through the MAPK/ERK pathway." (PMID 38139406, 2023). "In the present study, we report that CCS is highly expressed in breast cancer tissues and invasive breast cancer cells and promotes cell proliferation and migration." (PMID 31024318, 2019). "Here, we found CCS was highly expressed in breast cancer, where it promoted breast cancer cell proliferation and migration." (PMID 31024318, 2019). "Next, we sought to explore the role DC_AC50, a potent and selective CCS inhibitor, in breast cancer." (PMID 31024318, 2019). "As expected, overexpression of CCS accelerated breast cancer cell migration in a wound healing assay." (PMID 31024318, 2019). "In summary, these results indicated that CCS promotes the growth and migration of breast cancer cells via regulating the ERK1/2 activity mediated by ROS." (PMID 31024318, 2019). "Taken together, our results suggest that CCS plays an important role in promoting breast cancer cells migration." (PMID 31024318, 2019). "CCS was differentially expressed in several breast cancer cell lines, including MCF-7, T47D, MDA-MB-231, and SUM159." (PMID 31024318, 2019). "To determine the role of CCS in human breast cancer, we first examined the expression of CCS utilizing Gene Expression Omnibus (GEO) profiles; we found that the expression of CCS was higher in breast cancer tissue than in noncancerous tissue (GSE9574)." (PMID 31024318, 2019). "In all, we show that CCS not only plays a vital role in cell proliferation, but it also drives breast cancer migration." (PMID 31024318, 2019). "We found that the expression of CCS was higher in invasive ductal carcinoma than in ductal carcinoma, suggesting the potential role of CCS in promoting breast cancer migration." (PMID 31024318, 2019). "Furthermore, we found that inhibition of CCS by shRNA or an inhibitor blocks breast cancer proliferation and migration by triggering ROS mediated ERK activity." (PMID 31024318, 2019). "Next, we explore the role of CCS in the motility of the breast cancer cells." (PMID 31024318, 2019). "Interestingly, we revealed a novel function of CCS in regulating migration of breast cancer cells by transwell and wound healing assays." (PMID 31024318, 2019). "To validate these findings, we checked CCS expression in various breast cancer cells lines." (PMID 31024318, 2019). "In this study, we utilized MDA-MB-231 cells (triple-negative breast cancer) and MCF-7 cells (estrogen receptor positive breast cancer) as human cell line models and identified a novel function and mechanism of CCS in facilitating breast cancer cell proliferation and migration." (PMID 31024318, 2019). "Therefore, this study aimed to explore the critical role and molecular mechanism of CCS in migration and proliferation of breast cancer." (PMID 31024318, 2019).
breast cancer (continued). "We identified 13 members of the copper transport system associated with the occurrence, progression, and mortality of breast cancer, including SLC31A1, DMT1, ATP7A, ATP7B, MTs, GSH, ATOX1, CCS, COX17, SCO1, SCO2, and COX11." (PMID 39676279, 2024). "Bioinformatics analyses confirmed the positive correlation of breast cancer patients’ survival with AKT activation and up-regulation of CCS." (PMID 36454513, 2023). "To validate the role of MAPK signaling in the process of CCS-induced migration and proliferation in breast cancer cells, we first reactivated ERK by transfecting exogenous HA tagged MEK into MDA-MB-CCS-KD cells." (PMID 31024318, 2019). "CCS, a co-enzyme of SOD1, is a critical component of the oxidation–reduction system in cancer, and its differential expression in different types of breast cancer suggests a relationship between CCS and cancer cell growth and migration." (PMID 31024318, 2019). "However, the precise role of CCS in migration and proliferation of breast cancer cells is unknown." (PMID 31024318, 2019). "Nevertheless, both genes follow cancer-specific patterns of amplification, with Atox1 and CCS being amplified at a maximal level in kidney renal-cell carcinoma (KIRC) (23.1%) and breast cancer (BRCA) (18.1%) diseases, respectively." (PMID 31575544, 2019). "However, the function and clinical significance of CCS in breast cancer remain unclear." (PMID 31024318, 2019). "We found that the expression of CCS was higher in breast cancer tissue than in noncancerous tissue, suggesting the potential role of CCS in breast cancer cell proliferation." (PMID 31024318, 2019). "CCS expression was also significantly higher in breast cancer tissue than in noncancerous tissue in the Cancer Genome Atlas (TCGA)." (PMID 31024318, 2019). "Interestingly, we observed the same expression profile of AKT and CCS mRNAs also in the claudin low-breast cancer, characterized by the lack of HER2 and the expression of EMT genes." (PMID 36454513, 2023). "Cell number counting assays showed that knockdown of CCS significantly inhibited the proliferation of metastasis-prone breast cancer cell lines MDA-MB-231 but did not have any effect on the proliferation of breast cancer MCF-7 cells or normal BEAS-2B cells." (PMID 31024318, 2019).
amyotrophic lateral sclerosis (6 papers, 2019 to 2025). Amyotrophic lateral sclerosis (ALS) is a neurodegenerative disease characterized by progressive muscular paralysis reflecting degeneration of motor neurons in the primary motor cortex, corticospinal tracts, brainstem and spinal cord. "For instance, CCS deficiency has been associated with amyotrophic lateral sclerosis (ALS)." (PMID 40149738, 2025). "Differential methylation was reported in RAD9B and C8orf46, CCNF, DPP6, RAMP3, and CCS genes in monozygotic twins and triplets discordant for amyotrophic lateral sclerosis." (PMID 34200232, 2021). "Indeed, a mutation in CCS that disturbs SOD1 metallation has been linked to familial forms of amyotrophic lateral sclerosis (ALS), which is characterized by similar SOD1 aggregate pathology as reported recently in PD." (PMID 30791479, 2019). "Furthermore, CCS also functioned as a potential tumor promoter in a variety of cancers and several protein-misfolding diseases, including AD and amyotrophic lateral sclerosis, which may play an essential role in AD development." (PMID 39559883, 2024). "In amyotrophic lateral sclerosis (ALS), difficulties arise in the interaction between the copper chaperone of superoxide dismutase (CCS) and mutant copper-zinc superoxide dismutase (SOD1)." (PMID 38605864, 2024). "CCS proteins were identified in the human first time which transferred, interfere and balanced copper to SOD and plan a strategy for reducing or preventing amyotrophic lateral sclerosis (ALS)." (PMID 36982229, 2023).
leukaemia (3 papers, 2017 to 2023). "Moreover, inhibiting Atox1 delivery to CCS protein by small molecules was effective in killing breast, lung, leukaemia, head, and neck cancer cells in vitro and in a mouse xenograft model, while having only minimal effects on healthy cells." (PMID 36299299, 2022). "Inhibition of copper transport proteins AtoxI and CCS by small molecular inhibitor DC_AC50 can reduce growth of lung, leukaemia, breast and head/neck cancer cells without affecting normal tissues in mice." (PMID 28244639, 2017).
Wilson disease (3 papers, 2010 to 2022). A very rare inherited multisystemic disease presenting non-specific neurological, hepatic, psychiatric or osseo-muscular manifestations due to excessive copper deposition in the body. "CCS encodes a copper ion binding protein and its mutations are associated with disfunctions of copper metabolism resulting in Wilson disease, a rare inherited disorder that causes excess accumulation of copper in several organs." (PMID 35580588, 2022). "Erythrocyte CCS content may prove useful as a biomarker for assessing Cu overload and as a diagnostic test for disorders of Cu overload such as Wilson’s disease." (PMID 20717526, 2010). "The pathology generated by suppression of Atox1 or CCS gene in Drosophila neuronal tissues can serve as a powerful and reliable model system for Menkes and Wilson's diseases in human." (PMID 31575544, 2019).
colon cancer (2 papers, 2011 to 2021). "Previously, we mapped 15 Susceptibility to colon cancer (Scc) loci using CcS/Dem (CcS) RC strains, derived from the ‘background’ strain BALB/cHeA (BALB/c, resistant) and ‘donor’ strain STS/A (STS, susceptible)." (PMID 21390212, 2011). "The orthologous regions of 11 out of 13 human colon cancer susceptibility loci are polymorphic in the OcB or CcS strains that were tested for lung tumor susceptibility." (PMID 21390212, 2011). "The donor strain chromosomal regions of the CcS strains tested for colon tumor susceptibility comprised together about 40–50% of the genome, which is similar to the total proportion of the genome of the OcB strains tested for lung tumor susceptibility." (PMID 21390212, 2011). "Indeed, susceptibility to lung cancer (Sluc) loci underlying the extreme susceptibility or resistance of such CcS/Dem strains, mapped in 226 (CcS-10×CcS-19)F2 mice, co-localize with susceptibility to colon cancer (Scc) loci." (PMID 21390212, 2011). "The first is colon tumor susceptibility 9 (Scc9) locus, which was previously mapped in BALB/c × CcS crosses, and the second gene is angiogenesis by VEGF QTL 1(Angvq1), which was mapped by using BXD strains." (PMID 34294033, 2021). "The extreme susceptibility or resistance to lung tumors observed in the CcS strains, concordant to colon tumor susceptibility, has been supported by results from crosses of CcS-19, CcS-11, CcS-10 and CcS-20 with (BALB/c×FVB)F1 mice (tested due to the small number of available CcS mice)." (PMID 21390212, 2011).
Diabetes (2 papers, 2014 to 2023). "As the down-regulation of CCS in diabetes could well impair its ability to deliver copper to SOD1, we investigated whether SOD1 activity was altered in diabetes." (PMID 24927960, 2014). "The hearts of patients with diabetes displayed impaired mitochondrial copper regulation, as reflected in decreased mRNA and/or protein levels and altered mitochondrial translocation of copper chaperone proteins, including COX17, COX11, and mitochondria-resident CCS." (PMID 36774340, 2023).
lung carcinoma (2 papers, 2011 to 2022). "The orthologous regions of seven of them are polymorphic in OcB or CcS strains tested for lung cancer susceptibility." (PMID 21390212, 2011). "In lung cancer cells, the silencing of circ-CCS led to the upregulation of miR-383, which suppressed cell proliferation, promoted apoptosis, and prevented tumorigenesis." (PMID 36313570, 2022). "In lung cancer cells, upregulation of circ-CCS resulted in the overexpression of E2F7, which promotes cell expansion." (PMID 36313570, 2022).
bacteremia (1 paper, 2018). "The main objective was to explore the distribution of CCs and virulence genes according to source of bacteremia." (PMID 30319561, 2018).
bone metastasis (1 paper, 2020). Transfer of a neoplasm from its primary site to bones. "Univariate Cox regression analyses revealed that age at diagnosis, tumor grade, primary site, CEA, radiotherapy, chemotherapy, N stage, histology type, bone metastasis, and brain metastasis were correlated with OS and CCS in both PTR group and non-PTR group (all p < 0.05)." (PMID 32746835, 2020).
campylobacteriosis (1 paper, 2021). Infections with bacteria of the genus campylobacter. "However, CCs that commonly cause campylobacteriosis (e.g., ST-21, ST-45, ST-828 CCs) are generalist lineages, which is challenging for genomic source attribution if the CCs alone were to be used for source attribution." (PMID 34835426, 2021).
cardiomyopathy (1 paper, 2016). A disease of the heart muscle or myocardium proper. "Copper Chaperone for Superoxide Dismutase (CCS) plays a role in copper delivery to tissues; disturbances in copper homeostasis mediates cardiomyopathy." (PMID 26792056, 2016).
cognitive decline (1 paper, 2025). "Although increased SOD has been reported in the brain and blood, this is the first study linking alterations in SOD1 and CCS in platelets to early cognitive decline in AD." (PMID 40189792, 2025).
Cognitive impairment (1 paper, 2025). Abnormal cognition is characterized by deficits in thinking, reasoning, or remembering. "Notably, two genes, BCHE and CCS, along with biomarkers such as carotene, vitamin E, and bilirubin, demonstrate a significant relationship between psychiatric disorders and cognitive impairment." (PMID 40002349, 2025).
copper transport disorder (1 paper, 2021). "In addition, the total protein and RNA extracted from the rat liver tissues were examined, and the results showed that the expression of ATP7B and superoxide dismutase copper molecular chaperone CCS was significantly reduced after copper accumulation, suggesting a copper transport disorder." (PMID 34135753, 2021).
depression (1 paper, 2024). "Based on this, three-step SMR and colocalization analyses identified ITIH3 and CCS as being related to the risk of developing depression, while CTSS and DNPH1 are related to the onset of schizophrenia." (PMID 38637810, 2024). "Through coloc analysis, ITIH3 was conclusively associated with the onset of depression, CCS exhibited associations with depression at both the gene and protein levels, and CTSS and DNPH1 were implicated in the onset of schizophrenia at both the gene and protein levels." (PMID 38637810, 2024). "A total of three such sites were identified: CCS for depression and CTSS and DNPH1 for schizophrenia." (PMID 38637810, 2024). "Through drug target predictions, we found that copper and zinc ions can bind to CCS, demonstrating their potential as therapeutic drugs, which may represent a novel treatment direction for depression." (PMID 38637810, 2024).
ductal carcinoma (1 paper, 2019). "In addition, we also found that the expression of CCS was higher in invasive ductal carcinoma (IDC) than in ductal carcinoma (DCIS) (GSE21422)." (PMID 31024318, 2019).
fungal infection (1 paper, 2014). "In present study, we showed that the expression of CCS in chloroplast was transiently blocked in ripe fruits by fungal infection, suggesting a possibility that plastid IPP is available for the synthesis of sesquiterpene when the ripe fruits were challenged with a fungus." (PMID 25286411, 2014). "GGPS and CCS were detected only in the ripe fruit, in which the clear induction of GGPS was observed upon fungal infection." (PMID 25286411, 2014).
listeriosis (1 paper, 2018). A bacterial infection caused by Listeria monocytogenes. "Of particular concern is the isolation of isolates within several CCs associated with severe clinical infections, particularly CC1, CC4, and CC6, which have been shown to be strongly associated with human listeriosis in a comparison of clinical CCs to food-isolated CCs." (PMID 29742151, 2018).
lymphoma (1 paper, 2016). A malignant (clonal) proliferation of B- lymphocytes or T- lymphocytes which involves the lymph nodes, bone marrow and/or extranodal sites. "The main finding of this study is that by reproducing in vitro a condition of in vivo hyperCHO, lymphoma lymphoblastic cells overexpressed genes for antioxidant proteins (SOD1, SOD2, CCS, GSR, GSS and CAT) with the only exception of GRX2." (PMID 26754536, 2016).
mesenchymal tumor (1 paper, 2024). "It was noted that circ-CCS could downregulate ATG10 by targeting miR-197-3P, and the autophagy-promoting effect of circ-CCS on mesenchymal tumor cells was reversed after knockdown of miR-197-3p." (PMID 38887520, 2024).
neuroblastoma (1 paper, 2025). Neuroblastoma (NB) is the most common solid, extracranial childhood tumor. "CCS deficiency has been linked to increased Aß production in a SHSY5Y neuroblastoma model." (PMID 40189792, 2025).
Parkinson disease (1 paper, 2009). A progressive degenerative disorder of the central nervous system characterized by loss of dopamine producing neurons in the substantia nigra and the presence of Lewy bodies in the substantia nigra and locus coeruleus. "For example, a search for Parkinson disease returns 12 mitochondrial DG with interactions to 24 predicted DG (e.g. CCS, MECR, PRKAR2B)." (PMID 19390613, 2009).